RAD51C (RAD51 paralog C)
Diseases named in the same sentence as RAD51C in open-access papers (continued):
Sharing a sentence is not in itself a finding about the gene and the disease.
ovarian carcinoma (continued). "RAD51C is also involved in DNA repair by initiating HR when DNA damage occurs with pathogenic variants conferring higher risk of breast and ovarian cancer." (PMID 38700789, 2024). "Notably, gene amplifications and pathogenic variants in RAD51C have been linked to breast and ovarian cancers." (PMID 39635126, 2024). "The RAD51C c.145+3A>C variant was detected in a proband diagnosed with ovarian cancer at 63 years." (PMID 37444530, 2023). "In addition, RAD51C methylation appears to be a positive predictive biomarker of PARP inhibitor response in ovarian carcinomas, where loss of methylation even in one copy of the gene is sufficient to confer resistance to this inhibitor." (PMID 36293346, 2022). "We show significant correlation of mutations in BRCA1, BRCA2, and RAD51C with ovarian cancer risk." (PMID 33670479, 2021). "In addition, individuals with a RAD51 Homolog C (RAD51C) mutation have an increased risk to develop ovarian cancer." (PMID 35052761, 2021). "Furthermore, the relative risk of ovarian cancer associated with RAD51C and RAD51D was comparable to BRCA2, with odds ratios for all three genes of approximately five." (PMID 33926482, 2021). "In a population-based cohort and a screening trial of individuals at high risk of ovarian cancer, both RAD51C and RAD51D were shown to be moderately susceptible to ovarian cancer, suggesting the usefulness of these genes alongside BRCA1/2 for the prediction of susceptibility to ovarian cancer." (PMID 34838098, 2021). "The same study also found that RAD51C silencing was associated with sensitivity to PARP inhibitors in ovarian cancer, confirming that other members of the FA/HR pathway may also have utility as patient stratification biomarkers." (PMID 36046263, 2020). "RAD51C (FANCO) has been shown in multiple studies to be an ovarian cancer susceptibility gene." (PMID 36046263, 2020). "Evidence was provided for the newer ovarian cancer-associated genes, such as RAD51C/RAD51D/BRIP1, which were associated with ovarian cancer risks of 5.8–11% and already met the requirement for risk-reducing salpingo-oophorectomy, which is recommended for patients with > 5% ovarian cancer risk." (PMID 31472684, 2019). "RAD51C mutations c.93delG and c.837+1G>A were observed at a combined frequency of 1.0% among unselected ovarian cancer patients and at 2.1% frequency among breast and ovarian cancer families and associated with an increased risk of ovarian cancer." (PMID 28874143, 2017). "Moreover, six RAD51C monoallelic mutations, which predisposed to breast and ovarian cancer, were identified in German families." (PMID 27037238, 2016). "However, the susceptibility of RAD51C heterozygous mutation carriers to breast and ovarian cancer has been a topic of debate." (PMID 27037238, 2016). "Similarly, Meindl and associates analyzed 1,100 German families with gynecological malignancies and identified 6 monoallelic pathogenic mutations in RAD51C that confer an increased risk for both breast and ovarian cancers." (PMID 26075229, 2015). "Finally, Blanco and colleagues recently screened a large series of 516 BRCA1/BRCA2-negative patients from breast and/or ovarian cancer families for RAD51C mutations and identified 3 germline pathogenic mutations." (PMID 26075229, 2015). "Sixteen different FA genes have now been identified whose products act in a common pathway of DNA interstrand crosslink repair, and some of them (including BRCA2/FANCD1, BRIP1/FANCJ, PALB2/FANCN, and RAD51C/FANCO) have also been described as breast and ovarian cancer susceptibility genes." (PMID 24465539, 2014). "The identification of a series of genes that are involved in the BRCA-FA DNA repair pathway inspired more systematic searches for other pathway components, which resulted in the discovery of two further prominent ovarian cancer risk genes in 2011 and 2012: RAD51C and RAD51D." (PMID 23344037, 2013).
ovarian carcinoma (continued). "In a subsequent, but larger, Finnish study, RAD51C mutations were identified in ovarian cancer families only, while in a recent Spanish study, identified RAD51C mutations in 1.3% of breast and ovarian cancer families, with mutations in families with breast cancer cases only, were rare." (PMID 23586058, 2013). "Several studies have reported RAD51C causal mutations in breast and ovarian cancer predisposition." (PMID 24139550, 2013). "Rare mutations in RAD51C have been implicated in breast and ovarian cancer." (PMID 23704328, 2013). "Hereditary ovarian cancer is probably underestimated, since recent studies highlight new susceptibility genes (RAD51C, RAD51D, PALB2) that might predispose for ovarian cancer, but their exact prevalence is still under investigation." (PMID 23536787, 2013). "RAD51C has now emerged as an ovarian cancer susceptibility gene." (PMID 22415235, 2012). "Thus, there are multiple studies and evidence that RAD51C is a rare ovarian cancer predisposition gene important in both breast and ovarian cancers in HBOC families." (PMID 21980511, 2011). "In addition to 13.7% of deleterious germline BRCA1/BRCA2 carriers, we identified 7.4% additional patients with pathogenic germline variants in other genes predisposing for ovarian cancer, namely RAD51C, RAD51D, and MSH6, representing 35% of all pathogenic germline variants." (PMID 33008098, 2020). "Importantly, mono-allelic mutations in certain FA genes including FANCD1 (BRCA2), FANCS (BRCA1), FANCN (PALB2), FANCM, FANCJ (BRIP1), and FANCO (RAD51C) that are believed to operate downstream in the pathway and implicated in HR are associated with sporadic breast and ovarian cancer." (PMID 30813363, 2019). "Similar to pathogenic RAD51C variants, RAD51D-associated ovarian cancer risk remains low at younger ages (cumulative risk to age 50: 0.8%) but rises markedly thereafter." (PMID 41528496, 2026). "Background/Objectives: Germline pathogenic variants (GPVs) in PALB2, RAD51C, and RAD51D increase breast cancer (BC) and ovarian cancer (OC) risk." (PMID 40428378, 2025). "In ovarian cancer, pathogenic variants in BRCA1, BRCA2, RAD51C, RAD51D, and PALB2 predict PARP inhibitor efficacy, but this has not been established for other HRR-related genes." (PMID 40069561, 2025). "In terms of other PARP inhibitors, RAD51C and RAD51D mutations predicted response to treatment with rucaparib patients with relapsed ovarian cancer in a post hoc exploratory analysis of ARIEL2." (PMID 39695768, 2024). "RAD51 paralogues (RAD51B, RAD51C, RAD51D, XRCC2, and XRCC3) have recently been implicated in breast and ovarian cancer predisposition." (PMID 38360632, 2024). "The estimated risk associated with RAD51C and RAD51D were odd ratios of 5.2 (95% CI, 1.1 to 24) and 12 (95% CI, 1.5–90), respectively, and confirmed their strong association with ovarian cancer." (PMID 39202057, 2024). "Associations of RAD51C and RAD51D germline pathogenic variants (GPVs) with breast and ovarian cancer predisposition have been recently reported and are of interest." (PMID 39202057, 2024). "Among women carrying RAD51C alterations, 27.4% (31 of 113) had received a diagnosis of ovarian cancer." (PMID 38648056, 2024). "This study evaluated the prevalence of RAD51C and RAD51D genes in Chinese high-risk breast and/or ovarian cancer patients." (PMID 39202057, 2024). "For RAD51C and RAD51D PGVs carriers, it is estimated: (i) the absolute risk of BC is 10–40% and (ii) the absolute risk of epithelial ovarian cancer is 10–20%." (PMID 38672070, 2024). "The association of RAD51C and RAD51D GPVs with ovarian cancer susceptibility was first proposed in 2011." (PMID 39202057, 2024). "RAD51C, RAD51D, BRIP1, and PALB2 are genes known to be associated with a hereditary risk of ovarian cancer." (PMID 39695768, 2024).
ovarian carcinoma (continued). "The study will enrol women, unaffected by cancer, undergoing predictive testing at a familial cancer clinic for a pathogenic variant in a known breast cancer (BC) or ovarian cancer (OC) predisposition gene (BRCA1, BRCA2, PALB2, CHEK2, ATM, RAD51C, RAD51D)." (PMID 39107016, 2024). "The other case was a surgical ovarian cancer specimen with a germline RAD51C PV, showing HRD by GIS and HRP by RAD51 (32%)." (PMID 38648056, 2024). "The mutation frequencies for RAD51C and RAD51D in unrelated breast and/or ovarian cancer in European–American patients were 0.45% and 0.26%, respectively." (PMID 39202057, 2024). "Pathogenic variants (PVs) in BRCA1, BRCA2, PALB2, RAD51C, RAD51D, and BRIP1 cancer susceptibility genes (CSGs) confer an increased ovarian cancer (OC) risk, with BRCA1, BRCA2, PALB2, RAD51C, and RAD51D PVs also conferring an elevated breast cancer (BC) risk." (PMID 38334999, 2024). "Mutation frequencies of RAD51C and RAD51D for unselected ovarian cancer patients ranged from 0.2% to 1.1% and 0.35% to 1.1%, respectively." (PMID 39202057, 2024). "RAD51C and RAD51D germline alterations have been associated with increased ovarian cancer risk, whereas their contribution to BC risk is less clear." (PMID 37347260, 2023). "Mutations in RAD51B, RAD51C, RAD51D and XRCC2 are known to cause hereditary breast/ovarian cancer and Fanconi anemia." (PMID 37344587, 2023). "The contribution of the RAD51C and RAD51D deleterious variants to ovarian cancer has been previously established by numerous studies, but their role in BC predisposition is now emerging." (PMID 37628581, 2023). "BRIP1 is instead included on the corresponding gene panel for ovarian cancer predisposition, together with BRCA1, BRCA2, PALB2, RAD51C, RAD51D and the Lynch syndrome genes." (PMID 37563628, 2023). "The catalytic glutamate residue of RAD51 (RAD51E163) that is required for cleavage of the covalent β-γ phosphate bond of ATP is conserved in RAD51B (E144) and RAD51C (E161), and RAD51CE161 mutations have been linked to breast/ovarian cancers." (PMID 37344587, 2023). "Germline PVs in the HR-related genes BRIP1, PALB2, RAD51C and RAD51D have an established role in increasing a patient's risk of ovarian cancer." (PMID 36805919, 2023). "For the 759 patients with a personal and/or familial history of only ovarian cancer, as expected, BRCA1/2 genes were the most frequently mutated, followed by RAD51C and RAD51D." (PMID 37444530, 2023). "Pathogenic variants in BRCA1/2 are also associated with ovarian cancer risk, as are pathogenic variants in PALB2, RAD51C, and RAD51D." (PMID 36765408, 2023). "BRCA1 and BRCA2 were shown to be susceptibility genes for ovarian cancer, and the BRIP1, RAD51C, rad51D and mismatch repair genes also play a role in this disease." (PMID 35910206, 2022). "Recently, 21 founder and recurrent mutations in BRCA1/2, PALB2, RAD51C, and CHEK2 genes have been analyzed in a large Polish case-control study including 2270 ovarian cancer patients and 1743 controls." (PMID 35313928, 2022). "In another study evaluating the contribution of RAD51 genes, small proportions of pathogenic mutations in RAD51C (14/3429, 0.41%) and RAD51D (12/3429, 0.35%) in invasive epithelial ovarian cancer were identified." (PMID 35608067, 2022). "In ovarian cancer, analysis of samples from the ARIEL2 trial of rucaparib maintenance therapy found RAD51C and RAD51D mutations as well as high-level BRCA1 promoter methylation to be associated with PARPi sensitivity." (PMID 36970052, 2022).
ovarian carcinoma (continued). "Promoters of BRCA1 and RAD51C are frequently methylated in ovarian cancer, which results in a “BRCAness” phenotype that confers sensitivity to PARPis." (PMID 36970052, 2022). "New genes (RAD51C, RAD51D, and PALB2) have been identified as increasing susceptibility to ovarian cancer, but further research is required to investigate this." (PMID 35805770, 2022). "Two breast cancer women that are double heterozygotes (DH) for both BRCA1/BRCA2, one ovarian cancer case DH for BRCA1/RAD51C, and another breast and colorectal cancer who is DH for BRCA2/PMS2 were identified in our cohort." (PMID 36232793, 2022). "Ovarian cancers with germline or somatic mutation of BRCA1 or BRCA2, mutation of RAD51C or RAD51D, methylation of BRCA1, or high LOH have all been reported to respond to PARP inhibition." (PMID 35223797, 2022). "We have investigated RAD51C and RAD51D, hereditary ovarian cancer risk genes, in French Canadians of Quebec, Canada." (PMID 35565380, 2022). "In fact, in the ARIEL2 trial of the PARP inhibitor rucaparib in ovarian cancer, tumor biopsies revealed positive associations between alterations in BRCA1 or RAD51C, high genomic loss of heterozygosity (gLOH), and increased response to rucaparib." (PMID 35626165, 2022). "Recently, we found that pathogenic founder/recurrent germline mutations in 4 genes (BRCA1, BRCA2, RAD51C, PALB2) are responsible for 12.5% of ovarian cancer cases among unselected patients in the Polish population." (PMID 35313928, 2022). "Other genes implicated in ovarian cancer, BRIP1, RAD51D, PALB2, and RAD51C, had a yield of 1.1% (n = 12), 0.8% (n = 9), 0.3% (n = 3), and 0.09% (n = 1), respectively." (PMID 35971132, 2022). "In this study, p.Gln143Arg was detected in 0.7% of cases (n = 4), including one TN BC and two with a family history of ovarian cancer, and 0.2% of controls (n = 3), consistent with the observed RAD51C phenotypes." (PMID 35039523, 2022). "Collectively, germline mutations in BRIP1, RAD51C, and RAD51D account for around 2% of ovarian cancer cases." (PMID 35805770, 2022). "Genotyping of 21 mutations in BRCA1, BRCA2, RAD51C, PALB2, and CHEK2 genes was performed for 102 BOT patients, 167 cases of ovarian cancer G1, and 1743 healthy controls." (PMID 35313928, 2022). "More recently, additional genes associated with increased ovarian cancer risk have been identified, including BRIP1, RAD51C, and RAD51D." (PMID 33926482, 2021). "The aim of the study was to analyze the frequency and magnitude of association of 21 recurrent founder germline mutations in BRCA1, BRCA2, PALB2, RAD51C, and CHEK2 genes with ovarian cancer risk among unselected patients in Poland." (PMID 33670479, 2021). "Several founder mutations in the BRCA1, BRCA2, PALB2, RAD51C, and CHEK2 genes are associated with breast and ovarian cancer." (PMID 33670479, 2021). "We recommend that in Poland all women with ovarian cancer and first-degree female relatives should be tested for the panel of 18 founder mutations in BRCA1, BRCA2, PALB2, and RAD51C." (PMID 33670479, 2021). "In our cohort of 3422 index breast and ovarian cancer cases, we found RAD51B loss-of-function germline variants (9/3422 cases) to be almost as common as those affecting RAD51C and RAD51D (combined 16/3422 cases)." (PMID 34635660, 2021). "A personal history of ovarian cancer was most common among women with a PV in RAD51C (17.4%, 149/855) or RAD51D (16.3%, 74/455)." (PMID 33926482, 2021). "In our study we show and confirm that in Poland mutations in RAD51C and PALB2 are associated with ovarian cancer risk." (PMID 33670479, 2021).
ovarian carcinoma (continued). "The aim of the study was to analyze the prevalence and association of recurrent founder germline mutations in BRCA1, BRCA2, RAD51C, PALB2, and CHEK2 genes with ovarian cancer risk among unselected patients in the Polish population." (PMID 33670479, 2021). "In patients with ovarian cancer, instead, variants were identified mainly in the RAD50 and RAD51C genes." (PMID 34299313, 2021). "Genotyping of 21 mutations in BRCA1, BRCA2, RAD51C, PALB2, and CHEK2 genes was performed for all 2270 ovarian cancer patients and 1743 healthy controls." (PMID 33670479, 2021). "The data presented here for BRIP1, RAD51C, and RAD51D supports previous research demonstrating an increased risk of ovarian cancer for women with PVs in these genes." (PMID 33926482, 2021). "In order to better characterize the clinical presentation of women with a PV in a moderate penetrance ovarian cancer-risk gene, we evaluated women with a PV in BRIP1, RAD51C, or RAD51D identified during hereditary cancer genetic testing." (PMID 33926482, 2021). "The prevalence rate of BRIP1, RAD51C, or RAD51D pathogenic variants is about 1% in women with ovarian cancer." (PMID 32733558, 2020). "Patients with pathogenic mutations in these RAD51 regulator genes, particularly RAD51C and RAD51D, have a higher risk of developing ovarian cancer [RAD51C, OR 8.3 (95% CI 5.43–12.48); RAD51D, OR 3.17 (95% CI 1.31–7.42)]." (PMID 33015624, 2020). "In this study, we aim to gain insight in the germline mutation spectrum of ATM, BARD1, BRIP1, ERCC4, PALB2, RAD51C and RAD51D in breast and ovarian cancer families from Spain." (PMID 32756499, 2020). "Multiple gene panel studies have revealed that inherited breast and ovarian cancers rarely harbor germline mutations of FA genes, including BRIP1/FANCJ, PALB2/FANCN, and RAD51C/FANCO." (PMID 32269964, 2020). "The meta-analysis provides evidence supporting the pathogenicity of BRIP1, RAD51C, and RAD51D mutations in relation to ovarian cancer." (PMID 32359370, 2020). "As expected, LSTHi ovarian cancers were associated with BRCA1/2 mutations, BRCA1 or RAD51C promotor methylation and showed increased sensitivity to platinum-based chemotherapy." (PMID 32256521, 2020). "Mutations in BRIP1, RAD51C, or RAD51D are associated with an increased risk of developing ovarian cancer." (PMID 32733558, 2020). "Recently, several pieces of evidence showed that mutations in three genes involved in the homologous recombination DNA repair pathway, i.e., BRIP1, RAD51C, and RAD51D, are associated with a high risk of ovarian cancer." (PMID 32359370, 2020). "RAD51C and RAD51D are the most frequently mutated RAD51 paralogs in cancers and are most closely associated with increased ovarian cancer risk, although breast cancer risk is also increased." (PMID 33015624, 2020). "It is estimated that the frequency of RAD51C and RAD51D germline mutations in ovarian cancer patients is 3% and 5%, respectively." (PMID 33015624, 2020). "Based on the best available evidence, variants in BRCA1, BRCA2, BRIP1, RAD51C, RAD51D, and the mismatch repair genes confer ovarian cancer risks that warrant the consideration of risk-reducing surgery." (PMID 33086730, 2020). "Due to their role in BRCA1/BRCA2 DNA repair pathway, the loss-of-function mutations of RAD51C, RAD51D, BRIP1, and BARD1 genes have been generally considered as ovarian cancer susceptibility genes." (PMID 31366178, 2019). "BARD1, PALB2, and RAD51B variants have been identified in breast cancer families, whereas truncating RAD51C and RAD51D variants are mainly found in families with ovarian cancer or breast and ovarian cancer." (PMID 30689231, 2019). "RAD51 mutations have been identified in ovarian cancer; specifically, deleterious variants were shown in RAD51B, RAD51C, and RAD51D (nonsense, frameshift, and splice), with a predominance for RAD51C and RAD51D mutations." (PMID 31130614, 2019).